RANBP2 (RAN binding protein 2)
Diseases named in the same sentence as RANBP2 in open-access papers (continued):
Sharing a sentence is not in itself a finding about the gene and the disease.
juvenile myelomonocytic leukemia (2 papers, 2019 to 2022). A myelodysplastic/myeloproliferative neoplasm of childhood that is characterized by proliferation principally of the granulocytic and monocytic lineages. "In a genomic study of patients with juvenile myelomonocytic leukemia (JMML), 16 patients had no RAS variants, and in three of these that were 56 months of age or older, the researchers identified ALK/ROS1 tyrosine kinase fusions (DCTN1-ALK, RANBP2-ALK, and TBL1XR1-ROS1)." (PMID 36295546, 2022).
malignant melanoma (2 papers, 2014 to 2016). "For example, ANLN and PRC1 were mutated in cells derived from a malignant melanoma, and RANBP2, TTK, PP2R1A, and CEP192 were mutated in cells from pancreatic cancers." (PMID 27144335, 2016).
myeloid leukemia (2 papers, 2019 to 2023). A clonal proliferation of myeloid cells and their precursors in the bone marrow, peripheral blood, and spleen. "Except for ALCL, several hematopoietic neoplasms have been reported to have the following ALK fusion partners: CLTC, NPM1, SEC31A, SQSTM1, RANBP2, and EML4 in ALK-positive large B-cell lymphoma; TPM3 in ALK-positive histiocytosis; and RANBP2 in myeloid leukemia." (PMID 30941048, 2019). "To determine whether RanBP2 regulates ISG expression in immune cell lines, we depleted RanBP2 in human myeloid leukemia mononuclear (THP-1) cells using lentiviral delivered shRNA (“RanBP2 shRNA3”) and examined the expression of ISG mRNAs induced by IFN-α." (PMID 38203469, 2023).
neuropathies (2 papers, 2006 to 2021). "This is attributable to CNS-selective role of RANBP2, which may also underlie the pathogenesis of certain neuropathies." (PMID 33777149, 2021). "Emerging evidence supports that the CNS-selective effects of RanBP2 may also underlie the pathogenesis of certain neuropathies." (PMID 17069463, 2006).
osteosarcoma (2 papers, 2022 to 2023). A usually aggressive malignant bone-forming mesenchymal neoplasm, predominantly affecting adolescents and young adults. "To facilitate the initial experiments for investigating the sumoylation substrates of RanBP2, we expressed His-tagged SUMO2 (His6-SUMO2) in unmodified (wild type or “WT”) and RanBP2 dead E3 (“RanBP2-dE3”) human osteosarcoma (U2OS) cell lines, which we generated previously by CRISPR/Cas9." (PMID 38203469, 2023). "Finally, decreased expression of NUSAP1 seems to sensitize osteosarcoma cells to paclitaxel, as NUSAP1 interacts with the RanBP2-RanGAP1-UBC9 SUMO E3 ligase complex, allowing for accurate chromosomal segregation." (PMID 36478748, 2022).
pancreatic cancers (2 papers, 2013 to 2016). "We found a human mutation in the RBD4 of RanBP2, M2965I, which is reported to occur in 83 per cent of pancreatic cancers." (PMID 23536549, 2013).
atherosclerosis (1 paper, 2025). A disease characterized by the build-up of fatty material and calcium deposition in the arterial wall resulting in partial or complete occlusion of the arterial lumen. "We identified 12 lactylation-related genes that are more reliably associated with atherosclerosis: five upregulated genes (LSP1, IKZF1, MNDA, RCC2, and WAS) and seven downregulated genes (CSRP2, PPP1CB, CSRP1, HEXIM1, CALD1, PDLIM1, and RANBP2)." (PMID 40248193, 2025).
Cholestatic liver disease (1 paper, 2016). "RanBP2-mediated SUMOylation of SHP may be an effective therapeutic target for the treatment of cholestatic liver diseases and other BA-related hepatobiliary diseases." (PMID 27412403, 2016).
cyst (1 paper, 2024). A sac-like closed membranous structure that may be empty or contain fluid or amorphous material. "Possibly RanBP2, which has a SUMO1 E3-like activity and was highly connected to the keratin network in the cyst, plays a role in mediating the assembly of newly formed keratin bundles." (PMID 38891869, 2024).
diabetes (1 paper, 2006). "The presence of such compensatory mechanisms is also supported by the identification of a quantitative trait locus, which encompasses RanBP2, and modifies the expression of diabetes-related phenotypes." (PMID 17069463, 2006).
gastric cancer (1 paper, 2018). A primary or metastatic malignant neoplasm involving the stomach. "However, they failed to obtain a significant association between RANBP2 gene intron variant rs12614691 and gastric cancer risk." (PMID 29706609, 2018).
gestational diabetes (1 paper, 2020). Carbohydrate intolerance first diagnosed during pregnancy. "Moreover, from these genes, ATG7, DICER1, IGF1R and RANBP2 may play an important role in the genesis and growth of gestational diabetes mellitus and might serve as aberrantly methylation‐based or expression of miRNA‐targeting biomarkers for precise diagnosis and treatment of GDM in the future." (PMID 33085184, 2020).
glioma (1 paper, 2024). A benign or malignant brain and spinal cord tumor that arises from glial cells (astrocytes, oligodendrocytes, ependymal cells). "The research herein assessed the associations of RAN and RANBP2 gene polymorphisms with glioma susceptibility among 439 Chinese children." (PMID 39041645, 2024). "To investigate the relations between RAN/RANBP2 gene polymorphisms and glioma risk, we conducted a multicenter clinical study." (PMID 39041645, 2024). "Other potential functional gene polymorphism loci of RAN and RANBP2 will need to be evaluated in the search for novel glioma biomarkers." (PMID 39041645, 2024). "Females carrying the RANBP2 rs2462788 C>T polymorphism mutation appeared to have a reduced risk of developing gliomas (AOR = 0.69)." (PMID 39041645, 2024). "Although our results did not support the association of the selected SNPs with glioma, the association of additional RAN and RANBP2 SNPs with glioma remains worthy of further investigation." (PMID 39041645, 2024). "This study aimed to evaluate the association between RAN and RANBP2 gene polymorphisms and glioma susceptibility in Chinese children." (PMID 39041645, 2024). "Therefore, it is now necessary to further explore other potential functional gene polymorphism loci of RAN and RANBP2 to find novel glioma biomarkers." (PMID 39041645, 2024). "Stratification analysis between RANBP2 rs2462788 C>T polymorphism and glioma risk." (PMID 39041645, 2024). "The effects of RAN and RANBP2 gene polymorphisms on glioma susceptibility in Chinese children are currently unknown." (PMID 39041645, 2024). "Similarly, we investigated the association between the RANBP2 rs2462788 C>T polymorphism and glioma risk." (PMID 39041645, 2024). "RAN and RANBP2 gene polymorphisms with glioma susceptibility in Chinese children." (PMID 39041645, 2024). "Logistic regression model‐calculated odds ratio and 95% confidence interval were used to verify whether the gene polymorphisms (RAN rs56109543 C>T, rs7132224 A>G, rs14035 C>T, and RANBP2 rs2462788 C>T) influence glioma susceptibility." (PMID 39041645, 2024). "However, the associations of RAN and RANBP2 gene polymorphisms with glioma risk have not been examined." (PMID 39041645, 2024).
Hepatic steatosis (1 paper, 2026). Steatosis is a term used to denote lipid accumulation within hepatocytes. "Our study revealed significant nuclear/perinuclear co-localization of RanBP2 with SHP, which was strongly associated with serum hepatitis markers and the degree of hepatic steatosis in patients with MASH." (PMID 41438338, 2026).
Hodgkins lymphoma (1 paper, 2019). A heterogeneous group of malignant lymphoid neoplasms of B-cell origin characterized histologically by the presence of Hodgkin and Reed-Sternberg (HRS) cells in the vast majority of cases. "CD30-directed therapy using brentuximab vedotin is effective in relapsed Hodgkin lymphoma and ALCL,62,63 a strategy that may be useful in patients with CD30+RANBP2-ALK eIMS." (PMID 32914017, 2019).
latent infection (1 paper, 2010). "We have provided exquisite three-pronged evidences of RanBP2-independent Rev-function using acute HIV and lentiviral vector infection, latent infection model and Rev-dependent and -independent reporter systems." (PMID 21179483, 2010).
liver cancer (1 paper, 2021). An epithelial or non-epithelial malignant neoplasm that arises from the liver. "In liver cancer, SIRT1-mediated RANBP2 activation promotes progression of liver cancer." (PMID 33816306, 2021).
macular degeneration (1 paper, 2007). Loss of vision in the central portion of the retina (macula), secondary to retinal degeneration. "RPGRIP, RANBP2, NPM1, PDE6D, and NPHP5 were selected on the basis of protein interaction with RPGR or RPGRIP1 as these two proteins independently cause photoreceptor degeneration when mutated; ABCA4 was selected as a control gene, and because of its association with macular degeneration and RP." (PMID 17653054, 2007).
nasopharyngeal carcinoma (1 paper, 2020). A carcinoma arising from the nasopharyngeal epithelium. "RANBP2 known to regulate numerous cellular activities, is reported has an indivisible association with nasopharyngeal carcinoma through interacting with Epac142." (PMID 31949483, 2020).
renal cell carcinoma (1 paper, 2022).
retinal diseases (1 paper, 2007). "In this study, RPGRIP1, RANBP2, NPM1, PDE6D, NPHP5, and ABCA4 genes were selected on the basis of interaction with RPGR or RPGRIP1 or their implication in related retinal diseases, and were investigated as candidate genetic modifiers of XLPRA1." (PMID 17653054, 2007).
sarcoma (1 paper, 2022). A usually aggressive malignant neoplasm of the soft tissue or bone. "Our results as well as those of others implicate Six1 in sarcoma growth however its functional links to CTAG1B/A or to RANBP2 remain to be established and underscore the complexity of sarcoma biology." (PMID 35664317, 2022). "We mapped CTAG1B/A protein to sarcoma transcription pathways with gene set expression analysis (GSEA) and using independent samples, we immunohistochemically identified expression of at least two network neighbors, RANBP2, and TLE1, thus validating our approach." (PMID 35664317, 2022).
steatosis (1 paper, 2026). Increased lipid within the cytoplasm of cells. "We identified a strong association between nuclear SHP localization, hepatic inflammation, and steatosis, linking them to atypical PKCζ activation and perinuclear/nuclear aggregation of nucleoporin RanBP2 in liver tissue." (PMID 41438338, 2026).
synovial sarcoma (1 paper, 2022). "In the case of RANBP2, there are small yet distinct individual cells scattered throughout the field whereas in the case of TLE1, the entire field of vision is covered with positive cells (results not shown), similar to synovial sarcomas." (PMID 35664317, 2022).
Wilms tumor (1 paper, 2020). An embryonal neoplasm characterized by the presence of epithelial, mesenchymal, and blastema components. "Nevertheless, the effects of the RAN and RANBP2 gene polymorphisms on the tumorigenesis of Wilms tumor remain unclarified." (PMID 31949483, 2020). "In this study, three potentially functional polymorphisms (rs56109543 C>T, rs7132224 A>G, and rs14035 C>T) in the RAN and one (rs2462788 C>T) in the RANBP2 were chosen to investigate their association with Wilms tumor susceptibility." (PMID 31949483, 2020). "As far as we know, the current study is the first investigation regarding the association of RAN and RANBP2 gene polymorphisms with Wilms tumor susceptibility." (PMID 31949483, 2020). "Our results indicated that RAN and RANBP2 polymorphisms were associated with Wilms tumor susceptibility in Chinese children." (PMID 31949483, 2020). "More comprehensive researches with lager sample size were warranted to validate the association between RAN/RANBP2 gene polymorphisms and Wilms tumor risk." (PMID 31949483, 2020). "Thus, we conducted this study to examine the association of RAN and RANBP2 gene polymorphisms with Wilms tumor risk as well as cumulative effects of polymorphisms in the two genes." (PMID 31949483, 2020). "Moreover, stratified analysis indicated that RAN rs56109543 CT/TT genotypes, RAN rs7132224 AG/GG genotypes and RANBP2 rs2462788 CT/TT genotypes remarkably increased Wilms tumor susceptibility among the subgroups." (PMID 31949483, 2020). "What's more, the rs2462788 CT/TT in RANBP2 gene increased the chance of Wilms tumor in children aged ≤18 months, male and clinical stage I+II Wilms tumor." (PMID 31949483, 2020). "We conducted this study to explore the association of RAN and RANBP2 gene polymorphisms with Wilms tumor susceptibility has not yet been explored." (PMID 31949483, 2020). "Although our study is the first investigation about the association of RAN/RANBP2 gene SNPs with Wilms tumor risk, several flaws should be noted." (PMID 31949483, 2020).
tumor (30 papers, 2009 to 2025). "The patient underwent radical tumor resection, and genetic testing identified the presence of the RANBP2–ALK fusion." (PMID 39703852, 2024). "A study has shown that RANBP2 was identified as a critical target of YTHDF1, and YTHDF1 inhibited the apoptosis of tumor cells by regulating the expression of RANBP2 in CC." (PMID 37951987, 2023). "Our new findings show the fine tuning of OGA in HCC development by RANBP2 through the inactivation of CEBPα, and its function as a tumor suppressor is accordant with clinically relevant reports." (PMID 34298689, 2021). "In our HCC tissues (n = 54), RANBP2 levels were highly correlated with neoplastic grade (Edmondson–Steiner, p = 0.016), pT status (p = 0.042), and tumor size (p < 0.001)." (PMID 34298689, 2021). "According to the immunohistochemistry and Western blot results, HCC tissues had more RANBP2 than adjacent non-tumor ones." (PMID 34298689, 2021). "The variants in EXOG, RANBP2, RANBP6 and TNFRSF1B were sequenced in the tumour DNA of P1 to assess which allele of the gene was lost." (PMID 32357859, 2020). "Missense variants in four genes, EXOG, RANBP2, RANBP6 and TNFRSF1B, were identified in areas of LOH seen in the tumour from P1." (PMID 32357859, 2020). "In our study, the target protein p27kip1 mainly acts as a tumor-suppressor gene in the nucleus, RanBP2 and SUMO1 act as oncogenes by promoting the nuclear-cytoplasmic translocation and debilitate the G1-arrest brought by p27kip1 accumulation in the nucleus." (PMID 28882106, 2017). "Several studies suggested that its abdominopelvic origination, bigger tumor size, epithelioid morphology and RANBP2-ALK are possibly related to its aggressive course." (PMID 27460384, 2016). "However, the tumor cells exhibited round cell morphology in RanBP2 and ALK gene rearrangements cases." (PMID 40224630, 2025). "The human RGPD2 gene is also known as the RANBP2-like GRIP domain containing 2, which shares a high degree of sequence identity with mouse RANBP2, a sizeable nuclear pore protein that has been described to act as a tumor suppressor for its role in preventing chromosome segregation errors." (PMID 34113558, 2021). "In tumors with NPM1-ALK fusion, ALK protein may be detected in the nucleus and cytoplasm, while in RANBP2-ALK neoplasms, it shows nuclear membrane staining." (PMID 33237469, 2021). "Loss of the potentially pathogenic missense variant in RANBP2 in the tumour genome, suggests this variant is unlikely to be the cause of the PMP predisposition." (PMID 32357859, 2020). "In addition, some investigations have confirmed that RANBP2 is a tumor suppressor 43-45." (PMID 31949483, 2020). "RANBP2-ALK eIMS xenografts treated with brentuximab-vedotin, targeting CD30 + tumor cells, and crizotinib resulted in tumor shrinkage and prolonged disease-free survival." (PMID 35126101, 2021). "Unlike conventional IMT, EIMS is characterized by plump round-to-epithelioid tumor cells embedding in abundant myxoid stroma with inflammatory infiltrate, as well as immunopositivity for ALK, and frequent RANBP2-ALK fusion gene." (PMID 26178751, 2015).
tumor (continued). "RanBP2 is a nucleoporin with SUMO E3 ligase activity that functions in both nucleocytoplasmic transport and mitosis and its role as a novel tumor suppressor has been recently proposed." (PMID 32038817, 2009). "Several HBRV CIS are in the vicinity of tumor-suppressor genes, including PTEN, RANBP2, ORC1." (PMID 35632628, 2022). "Four genes (EXOG, RANBP2, RANBP6 and TNFRSF1B) harboured missense variants that fell in a region of LOH in the tumour from the father only, but none showed somatic loss of the wild type allele in the tumour." (PMID 32357859, 2020). "Only two mutations, RANBP2 P1380R in BLCAb001, and RYR2 E1859K in BLCAb002, were present in the PDXs but not in the primary tumor." (PMID 27823983, 2016). "However, another study has reported that ALK positivity might indicate a good prognosis, while patients with gene rearrangements involving both RAN binding protein 2 (RanBP2) and ALK exhibit a higher tumor recurrence rate and a relatively poor prognosis." (PMID 40224630, 2025). "RANBP2-ALK fusion likely plays the essential role in the carcinogenesis of this tumor, and ALK inhibitor is a promising treatment for this aggressive tumor regardless of its potential acquired resistance." (PMID 26178751, 2015).